STAT3 (signal transducer and activator of transcription 3)
Diseases named in the same sentence as STAT3 in open-access papers (continued):
Sharing a sentence is not in itself a finding about the gene and the disease.
lung adenocarcinoma (continued). "Elevated TF expression participated in MPE generation via its promotion of tumor metastasis and increase in vascular permeability in lung adenocarcinoma bearing activated Stat3." (PMID 24086497, 2013). "Based on these observations and the properties of TF on increasing vascular permeability, it is possible that TF is one of the downstream targets of IL-6/Stat3 signaling, which contributes to the pathogenesis of lung adenocarcinoma and MPE." (PMID 24086497, 2013). "Previously, we found that autocrine IL-6-induced Stat3 activation contributes to tumor metastasis of lung adenocarcinoma." (PMID 24086497, 2013). "Persistently activated or tyrosine-phosphorylated STAT3 (pSTAT3) is found in 50% of lung adenocarcinomas." (PMID 24260500, 2013). "Taken together, these findings indicate that, in lung adenocarcinoma bearing activated Stat3, MPE generation can be independently induced by TF or VEGF." (PMID 24086497, 2013). "Our results indicate IL-6/JAK2/Stat3 pathway also regulates TF expression, which is an important regulator for tumor formation, lung metastasis, and malignant effusion generation in lung adenocarcinoma bearing activated Stat3." (PMID 24086497, 2013). "The contribution of autocrine IL-6-activated Stat3 to MPE in lung adenocarcinoma is also through VEGF upregulation." (PMID 24086497, 2013). "We have found that Stat3 activated by autocrine IL-6 mediates the generation of malignant effusion via upregulation of VEGF in lung adenocarcinoma." (PMID 24086497, 2013). "STAT3 is persistently activated in a number of NSCLC cell lines as well as 50% of lung adenocarcinomas, with a trend toward higher pSTAT3 expression in tumors with bronchioloalveolar carcinoma or adenocarcinoma histology." (PMID 23251519, 2012). "Mutations in the kinase domain of the epidermal growth factor receptor result in STAT3 activation via the IL-6–JAK pathway in human lung adenocarcinoma." (PMID 21730976, 2011). "In addition, we conducted IHC staining on 108 lung adenocarcinoma tissues and assessed the association between the protein levels of SHH, DUSP13B, p‐STAT3, and EGFR gene mutation status." (PMID 39721017, 2025). "EGFR, the critical regulator of carcinogenesis in lung adenocarcinoma cells, may also be responsible for STAT3 phosphorylation in this context." (PMID 39985075, 2025). "The results above indicated that inhibition of the JAK2/STAT3 pathway triggered by SOCS1 might be mediated by PRDM5 in lung adenocarcinoma cells." (PMID 36127737, 2023). "In a lung adenocarcinoma model induced by the carcinogen urethane, genetic ablation of STAT3 from the lung epithelium led to an increased production of pro-inflammatory cytokines and enhanced function of natural killer (NK) cells that substantially inhibited urethane-induced lung carcinogenesis." (PMID 36672335, 2023). "Others have shown that overexpressed PCNP could result in activation of the STAT3/5 signaling pathway, thereby suppressing lung adenocarcinoma cell apoptosis." (PMID 35468892, 2022). "However, in Kirsten rat sarcoma and viral oncogene (KRAS)-mutant lung adenocarcinoma, STAT3 exerts an unexpected tumor-suppressive effect by sequestering NF-κB in the cytoplasm, thus decreasing IL-8 expression induced by NF-κB." (PMID 36557902, 2022). "In this review, we summarize the lung epithelial and infiltrating immune cells that express STAT3, the roles of STAT3 in K-ras mutant lung adenocarcinoma, and therapies that may be able to target STAT3." (PMID 35406557, 2022). "Similarly, activation of STAT3 and ERK pathways appeared to cause PD-L1 expression in lung adenocarcinoma." (PMID 34503167, 2021). "In lung adenocarcinoma cells, has-miR-320a can markedly inhibit tumor cell growth through suppressing signal transducer and activator of transcription 3 (STAT3) expression and its downstream signals, which was linked to the inhibition of cell growth in a xenograft mouse model of lung adenocarcinoma." (PMID 34071109, 2021).
lung adenocarcinoma (continued). "In lung adenocarcinoma clinical samples, the inverse correlation between E-cadherin and IL-6 expression, and the positive correlation between IL-6, vimentin and STAT3 protein phosphorylation confirmed the importance of the IL-6/STAT3/Snail axis described in animal models." (PMID 34361105, 2021). "Moreover, STAT3 was more highly expressed in lung adenocarcinoma tissues than in corresponding normal tissue." (PMID 32022328, 2020). "Inhibition of STAT3 feedback sensitized lung adenocarcinoma to MEK inhibition." (PMID 32872659, 2020). "Our findings suggest that BLN-A may be developed into a novel STAT3 inhibitor and as a potential therapeutic agent against lung adenocarcinoma." (PMID 32328177, 2020). "Indeed, genetic inhibition of both YAP1 and STAT3 decreased the stem cell-like features of lung adenocarcinoma cells, resulting in reduced proliferation and enhanced cisplatin sensitivity." (PMID 31137841, 2019). "Therefore, it can be concluded that PCNP can modulate apoptosis via STAT3/5 pathway in human lung adenocarcinoma cells." (PMID 30872582, 2019). "In addition, our findings reveal that PCNP mediates the proliferation, migration, and invasion of human lung adenocarcinoma cells via STAT3/5 and PI3K/Akt/mTOR signaling pathways." (PMID 30872582, 2019). "Interestingly, activation of the signal transducer and activator of transcription 3 (STAT3) pathway also induces ERβ expression in lung adenocarcinoma cells." (PMID 29970138, 2018). "Most interestingly, the expression of SOCS2 dose dependently reduced the interaction between IGF1R and STAT3 or STAT5, indicating that SOCS2 acts as a STAT3/STAT5 inhibitor that can competitively bind to IGF1R and thus can attenuate the IGF1-induced STAT3/STAT5 activity in lung adenocarcinoma cells." (PMID 29559623, 2018). "In contrast, STAT3 showed promoting effects of OSM in lung adenocarcinoma." (PMID 28626343, 2017). "The effect could be abrogated by suppressing STAT3 phosphorylation or silencing IL-11Rα in lung adenocarcinoma cells." (PMID 27922075, 2016). "In the present study, the phosphorylation inhibitor of STAT3 could inhibit the effect of IL-11 on promoting the colony formation and reducing apoptosis rate (early and later) of lung adenocarcinoma cells." (PMID 27922075, 2016). "However, STAT3 was constitutively acetylated in the A549 lung adenocarcinoma cell line, and constitutive localization of acetyl-STAT3 to mitochondria was detected." (PMID 28004755, 2016). "Our findings suggest thatDEGs encoding subunits of NADH, PRIM1, MCM3, MAPK1, STAT3, RAF1, and JAK1 might beassociated with the development of lung adenocarcinoma." (PMID 26840709, 2016). "Taken together, our results showed that activation of IL-11/IL-11R/STAT3 anti-apoptotic signaling could augment lung adenocarcinoma cells resistance to cisplatin-induced apoptosis by upregulating Bcl-2 and Survivin." (PMID 27922075, 2016). "Since various studies have now indicated an important role for the IL-6/STAT3 axis as a mediator of resistance to EGFR inhibition in lung adenocarcinomas, we have also analyzed whether IL-6 was upregulated in the cell models utilized here." (PMID 27248176, 2016). "Moreover, it was also reported that metformin was able to depress IL-6-induced EMT possibly by blocking STAT3 phosphorylation, thereby inhibiting the growth and metastasis of lung adenocarcinoma." (PMID 27105507, 2016). "The enhancement of STAT3 phosphorylation via IL-11 was also observed in lung adenocarcinoma cells." (PMID 27922075, 2016). "To verify whether EB inhibited STAT3 activation, we examined the phosphorylation of STAT3 in lung adenocarcinoma A549 cells using Western Blot analysis." (PMID 26010889, 2015). "We found that metformin could inhibit IL-6 induced EMT possibly by blocking STAT3 phosphorylation, suggesting a potential clinical use of metformin in treatment of lung adenocarcinoma." (PMID 24789104, 2014).
lung adenocarcinoma (continued). "We discovered that IL-6, via STAT3 phosphorylation, could promote lung adenocarcinoma cell invasion via EMT in vitro." (PMID 24789104, 2014). "Together, our data revealed that autocrine IL-6 could activate Stat3 and increase the level of TF expression in various lung adenocarcinoma cell lines." (PMID 24086497, 2013). "In this study, we investigated whether IFN-γ-transfected BMSCs combined with QSFZYL affects the progression of lung adenocarcinoma through the JAK2/STAT3 pathway through Western blotting and qPCR analyses of the expression of JAK2/STAT3 pathway-related proteins and genes in intervention groups." (PMID 40642092, 2025). "Besides, Ginsenoside Rh4 could inhibit the metastasis of Lung Adenocarcinoma via suppressing JAK2/STAT3 Signaling pathway." (PMID 38213735, 2024). "Thus, the current data suggested that IL-22 might directly promote lung adenocarcinoma growth by engaging STAT3 signaling." (PMID 30473538, 2018). "To better elucidate the mechanisms of chemoresistance induced by IL-11, we found that IL-11 could attenuate cisplatin-induced apoptosis rate of lung adenocarcinoma cells accompanied with the activation of anti-apoptotic STAT3 signaling including Bcl-2 and Survivin overexpression." (PMID 27922075, 2016). "Therefore, we speculate that the IL-6-induced EMT of lung adenocarcinoma cells may be due to activation of STAT3." (PMID 24789104, 2014). "In lung adenocarcinoma, IL-6 secreted by TAMs activates the JAK2/STAT3 pathway, and STAT3 can activate the expression of C/EBPβ, thereby enhancing the expression of IL-6." (PMID 40131539, 2025). "Analysis of the TISIDB database revealed a negative correlation between STAT3 expression and activated CD8+ T cell infiltration in lung adenocarcinoma (LUAD), suggesting STAT3’s role in immune evasion." (PMID 40347254, 2025). "In lung adenocarcinoma (LUAD), exosomal miR-19b-3p secreted by LUAD cells can target macrophage PTPRD, which inhibits PTPRD-mediated STAT3 dephosphorylation in macrophages, resulting in STAT3 activation and M2 polarization." (PMID 40612677, 2025). "Previous studies have shown that STEAP1 expression is upregulated in lung adenocarcinoma cells, where it regulates cellular epithelial–mesenchymal transition (EMT) through the (JAK2/STAT3) signaling pathway." (PMID 39991151, 2025). "A study of lung adenocarcinoma demonstrated that EML4-ALK fusion can upregulate p-STAT3 levels, then p-STAT3 upregulates PD-L1 expression by binding to the CD274 promoter." (PMID 38426097, 2024). "NSD3 formed protein trimer with PPP1CB and p‐STAT3, thus stimulating p‐STAT3 dephosphorylation by PPP1CB to suppress the transcription of HK2, which ultimately inhibited the Warburg effect in lung adenocarcinoma." (PMID 39119928, 2024). "Daphnetin inhibits the proliferation, clonal formation, migration, and invasion of lung adenocarcinoma A549 cells by inhibiting the activation of the MAPK, NF-κB, and STAT3 signaling pathways." (PMID 39469948, 2024). "Therefore, in this study, we investigated the role of the MAPK/STAT3/NF-κB signaling pathway in the anti-tumor effects of daphnetin and its mechanism in lung adenocarcinoma A549 cells, and clarified the anti-tumor effect of daphnetin and its related mechanism in lung adenocarcinoma A549 cells." (PMID 39469948, 2024). "For instance, STAT3 activity has been observed to be inhibited through Erk1/2- and p38-dependent pathways in human lung adenocarcinoma, while JNK inhibition reduces STAT3 serine phosphorylation in oral squamous cell carcinoma." (PMID 39273231, 2024). "Together, this study revealed the critical non‐epigenetic role of NSD3 in the regulation of STAT3‐dependent glycolysis, providing a piece of compelling evidence for targeting the NSD3/PPP1CB/p‐STAT3 in lung adenocarcinoma." (PMID 39119928, 2024).
lung adenocarcinoma (continued). "Meanwhile, IHC analysis was conducted to assess the protein expressions of p-JAK2, p-STAT3, Bcl-2, Snail, and PTPRO in tissue sections obtained from ten cases of clinical lung adenocarcinoma specimens." (PMID 38182570, 2024). "Based on the GSE164789 lung adenocarcinoma single-cell RNA-seq cohort, the variations in the expression of STAT3 and JAK1, the core genes in the IL6-JAK-STAT3 pathway, were calculated based on the developmental trajectory of MDSCs." (PMID 39049031, 2024). "X-ray radiation induced senescence and increased the expression of STAT3, Beclin1, and the LC3-II/LC3-I ratio in lung adenocarcinoma cells." (PMID 36834846, 2023). "To investigate the potential mechanism by which PRDM5 deregulation promoted the proliferation of lung adenocarcinoma cells, we tested the expression levels of components of the JAK2/STAT3 pathway in A549 cells overexpressing PRDM5." (PMID 36127737, 2023). "Our study suggests that deregulation of PRDM5 promotes the proliferation of lung adenocarcinoma cells by downregulating SOCS1 and then upregulating the JAK2/STAT3 signaling pathway." (PMID 36127737, 2023). "Accordingly, these results suggest that FIBP binds to STAT3 to enhance its transcriptional activity, thereby inducing EME1 expression in lung adenocarcinoma cells." (PMID 37564211, 2023). "Our study suggests that the low expression of PRDM5 promotes the proliferation of lung adenocarcinoma cells by downregulating SOCS1 and then upregulating the JAK2/STAT3 signaling pathway." (PMID 36127737, 2023). "Taken together, these findings demonstrate that FIBP is a novel positive regulator of STAT3 and controls STAT3-dependent EME1 expression in lung adenocarcinoma." (PMID 37564211, 2023). "Curcumin was developed as a novel inhibitor of the STAT3 pathway where treatment with curcumin suppressed the expression of phosphorylated STAT3 in a dose-dependent manner in normal broncho epithelial cells (AALE) and human lung adenocarcinoma cells (H441)." (PMID 37765192, 2023). "According to our results, overexpressed PRDM5 is likely to upregulate the promoter activity of SOCS1 and further suppress the JAK2/STAT3 pathway by inhibiting the phosphorylation of JAK2 and STAT3, thus repressing cell proliferation in lung adenocarcinoma." (PMID 36127737, 2023). "A study demonstrated that the lncRNA LOC389641 played an oncogenic role in lung adenocarcinoma through suppressing autophagy by reducing the expression of autophagy-related proteins, p-AMPK and LC3B via EGFR/MET/STAT3 signalling." (PMID 35379783, 2022). "In lung adenocarcinoma, JAK2/STAT3 activation contributes to EMT and the metastasis of cancer cells." (PMID 35818076, 2022). "Combined with our research basis, we tried to explore the possible mechanism of primary drug resistance in EFGR mutant lung adenocarcinoma through the interaction between the JAK/STAT1 and JAK/STAT3 pathway." (PMID 36185620, 2022). "Our previous study reported that α5-nAChR mediates lung adenocarcinoma (LUAD) epithelial-mesenchymal transition (EMT) and metastasis via STAT3/Jab1." (PMID 35971127, 2022). "For instance, the downregulation of PYCR1 inhibited the growth of lung adenocarcinoma cells by repressing the Janus kinase (JAK)-signal transducer and activator of transcription-3 (STAT3) signaling pathway." (PMID 34696668, 2021). "Opposite to the pro-EMP role of STAT3, STAT1 activation by OSM has been shown to reduce metastasis of lung adenocarcinoma by STAT1/HDAC1/PIAS4-mediated Slug repression." (PMID 34361105, 2021). "One of these studies reported that IL-11 treatment promoted lung adenocarcinoma cell growth and EMT through activation of the STAT3/HIF-1α/EMT signalling pathway." (PMID 34361105, 2021). "MiR-29b-3p is involved in the regulation of apoptosis, the cell cycle, and metastasis, and its targeting by lncRNA H19 transforms STAT3 (signal transducer and activator of transcription 3), and thus, promotes the survival and EMT of lung adenocarcinoma cells." (PMID 33412752, 2020).
lung adenocarcinoma (continued). "B7-H3-induced signaling includes at least three cascades: PI3K/AKT, JAK2/STAT3, and Raf/MEK/ERK1/2, which are also involved in epidermal growth factor receptor- (EGFR-) triggered signaling in lung adenocarcinoma cells." (PMID 33426073, 2020). "In another study, it was found that STAT3 and HER3 activation are interconnected in lung adenocarcinoma." (PMID 33327495, 2020). "In the current study, our data show that SOCS2 is involved in attenuating the IGF1-induced STAT3 and STAT5 activity in lung adenocarcinoma cells." (PMID 29559623, 2018). "In the study of lung adenocarcinoma, it was shown that JAK/STAT3 signaling pathway participated in the apoptosis of PC-9 cells induced by icotinib." (PMID 29541400, 2018). "Finally, we asked if ALT could inhibit STAT3 activation in other lung adenocarcinoma cells." (PMID 28740138, 2017). "In this study we provide novel evidence that enhanced IL-6 expression, via STAT3 phosphorylation, is a mechanism that can drive EMT and metastasis in lung adenocarcinoma." (PMID 24789104, 2014). "Collectively, our present results show that enhanced IL-6 expression, via STAT3 phosphorylation, is a mechanism of EMT in lung adenocarcinoma." (PMID 24789104, 2014). "To investigate this point, we first examined the effect of IL-6 on STAT3 tyrosine phosphorylation in A549 and HCC827 lung adenocarcinoma cells." (PMID 24789104, 2014). "In conclusion, we demonstrate that TF is regulated by Stat3 activation and is an important regulator for the generation of MPE in lung adenocarcinoma." (PMID 24086497, 2013). "We previously demonstrated that autocrine IL-6-activated Stat3 contributes to tumor metastasis and upregulation of VEGF, resulting in the generation of MPE in lung adenocarcinoma." (PMID 24086497, 2013). "The Stat3 phosphorylation was also inhibited by INC424 (JAK inhibitor) in CL 1-5, H1650 and PC14PE6/AS2 (AS2) lung adenocarcinoma cells; accordingly, TF expression was decreased in those cells." (PMID 24086497, 2013). "Together, we found that the expression of TF regulated by IL-6/JAK2/Stat3 signaling promotes tumor metastasis and MPE formation in an animal model of lung adenocarcinoma." (PMID 24086497, 2013). "Inhibitors of Jak2/Stat3, MEK/Erk and PI3-K/Akt pathways down-regulated IL-6 secretion in the lung adenocarcinoma PC14PE6/AS2 (AS2) cells, which spontaneously secreted IL-6 and possessed constitutively activated Stat3." (PMID 21122157, 2010). "In lung adenocarcinomas induced by MYC and/or K-rasG12D, tumors exhibited activation of the K-Ras/Stat3 signaling pathway." (PMID 18461184, 2008). "Common drivers in lung adenocarcinoma (but not lung squamous cell carcinoma) include EGFR and K-Ras mutations, which can serve as the activating signal upstream of STAT3." (PMID 41380973, 2025). "The five largest node targets identified were protein kinase 1 (AKT1), STAT3, JUN, interleukin-6 (IL-6), and mitogen-activated protein kinase 3 (MAPK3), which may be important targets for the treatment of lung adenocarcinoma with QSFZYL." (PMID 40642092, 2025). "We assess the effect of lung adenocarcinoma cells on TAM through detecting the expression of SHP2, p- STAT1, p-STAT3, p-STAT5, p-STAT6, IL-4, IL-10, Cathepsin-L, Cathepsin-S, Cathepsin-K and Arginase-1 in each group of THP1 cells cocultured with and without A549 cells by western blot." (PMID 38747738, 2024). "Exploring whether this mechanism similarly contributes to lung adenocarcinoma could open new therapeutic avenues, particularly for combined treatment strategies with ALK and STAT3 inhibitors." (PMID 39555099, 2024). "However, another research suggested that IFN-γ upregulates PD-L1 expression in lung adenocarcinoma cells through the PI3K/AKT and JAK/STAT3 pathways, which need for further research support to prove the potential of STAT3 in IFN-γ induced PD-L1 expression." (PMID 38426097, 2024).